MAST2 (microtubule associated serine/threonine kinase 2)
Description:
Appears to link the dystrophin/utrophin network with microtubule filaments via the syntrophins. Phosphorylation of DMD or UTRN may modulate their affinities for associated proteins. Functions in a multi-protein complex in spermatid maturation. Regulates lipopolysaccharide-induced IL-12 synthesis in macrophages by forming a complex with TRAF6, resulting in the inhibition of TRAF6 NF-kappa-B activation (By similarity).
Synonyms: KIAA0807; MAST205; MTSSK
Tractability: Small molecule: it belongs to a druggable protein family. Antibody: UniProt places it where antibodies can reach, with high confidence; its Gene Ontology location is reachable by antibodies, with medium confidence. PROTAC: UniProt records ubiquitination sites on it; ubiquitination databases record sites on it; its protein half-life has been measured.
Target class: Enzyme; AGC protein kinase group; Protein Kinase; Kinase; AGC protein kinase MAST family
Gene: Protein-coding gene on chromosome 1 (45,786,987 to 46,036,228, forward strand). Ensembl gene ENSG00000086015.
Subcellular location: Cytoplasm, cytoskeleton; Cell membrane
Subcellular location (Human Protein Atlas): Cytosol
Gene Ontology:
Molecular function: phosphatase binding; protein binding; ATP binding; magnesium ion binding; microtubule binding; protein serine/threonine kinase activity; protein kinase activity; protein serine kinase activity
Biological process: cytoskeleton organization; intracellular signal transduction; protein phosphorylation; regulation of interleukin-12 production; spermatid differentiation
Cellular component: microtubule cytoskeleton; cytoskeleton; plasma membrane
Genetic constraint (gnomAD): Loss-of-function variants: 69 observed, 146.47 expected, observed/expected ratio (o/e) 0.47, 90% interval 0.39 to 0.58. The upper end of that interval is the gene's LOEUF score, 0.58, which puts it in group 2 of 6, group 1 being the genes least tolerant of losing a copy. Missense variants: 1,998 observed, 2,272.6 expected, observed/expected ratio (o/e) 0.88, 90% interval 0.85 to 0.91. Synonymous variants: 833 observed, 881.28 expected, observed/expected ratio (o/e) 0.95, 90% interval 0.89 to 1.
Gene-disease validity (ClinGen):
ClinGen rates the evidence that MAST2 causes each of these diseases.
thrombotic disease (autosomal dominant): Limited. The formation of a blood clot in the lumen of a vessel or heart chamber; causes include coagulation disorders and vascular endothelial injury.
Homologues: Orthologues: chimpanzee MAST2 (99% identical), macaque MAST2 (97% identical), dog MAST2 (90% identical), mouse Mast2 (88% identical), rat Mast2 (88% identical), guinea pig MAST2 (82% identical), pig MAST2 (81% identical), tropical clawed frog mast2 (70% identical), zebrafish mast2 (66% identical), Drosophila melanogaster dop (40% identical), Caenorhabditis elegans kin-4 (32% identical), Caenorhabditis elegans wts-1 (10% identical), and 3 more. Paralogues in human: MAST4 (56% identical), MAST1 (53% identical), MAST3 (45% identical), LATS1 (14% identical), LATS2 (13% identical), DMPK (11% identical), SGK1 (9% identical), SGK3 (9% identical), STK32C (9% identical), MASTL (9% identical), STK32B (8% identical), SGK2 (7% identical), and 1 more.
Diseases named in the same sentence as MAST2 in open-access papers:
MAST2 is named in the same sentence as 24 diseases in open-access papers, as found by Europe PMC text mining. Sharing a sentence is not in itself a finding about the gene and the disease. The quoted sentences say what the papers report.
breast carcinoma (9 papers, 2013 to 2025). "An increased risk for breast cancer was also reported to be associated with nine SNPs (single nucleotide polymorphism) found in MAST2." (PMID 37569286, 2023). "The non-coding region of the MAST2 gene was mutated at a higher frequency than what reported in any previous WGS analysis of breast cancer." (PMID 33902690, 2021). "In the largest WGS study for breast cancer (BRCA-EU from The ICGC Breast Cancer Project), the mutation frequency of MAST2 was 1/569 (0.18%), which was significantly lower than our IBC cohort (Fisher’s test, Bonferroni adjusted p = 0.024)." (PMID 33902690, 2021). "Somatic alterations in the genes for MAST1 and MAST2 were discovered and characterized in material obtained from breast cancer samples." (PMID 37569286, 2023). "MAST2 gene rearrangements were previously noted in some breast cancers, and overexpression of MAST2 (or MAST1) gene fusions in breast epithelial cells led to increased proliferation in vitro and in vivo." (PMID 33902690, 2021). "In some breast cancer cells, MAST1 and MAST2 are fused with other proteins through recurrent gene rearrangements; these fusion proteins act as putative tumorigenic drivers." (PMID 30773781, 2019). "Interestingly, during preparation of this manuscript, recurrent gene rearrangements involving MAST2 and MAST1 were identified in breast cancer cell lines and tissues." (PMID 23717670, 2013).
liver cancer (4 papers, 2019 to 2025). An epithelial or non-epithelial malignant neoplasm that arises from the liver. "Overexpression of MAST2, an oncogene involved in tumor proliferation and survival, is linked to poor prognosis in liver cancer and represents another potential treatment target." (PMID 40227503, 2025). "In this study, we compared MAST2 expression in liver cancer patients and then evaluated its diagnostic value." (PMID 31882722, 2019). "This study firstly demonstrates the potentially diagnostic and prognostic significance of MAST2 in liver cancer patients." (PMID 31882722, 2019). "Our findings suggest MAST2 could be a novel diagnostic and prognostic biomarker for liver cancer patients." (PMID 31882722, 2019). "In this study, we explored the diagnostic and prognostic role of MAST2 in liver cancer patients." (PMID 31882722, 2019). "In total, MAST2 is a potential diagnostic and prognostic biomarker of liver cancer." (PMID 31882722, 2019). "We found that MAST2 highly expressed in liver cancer and thus, may have diagnostic value for this cancer, and its expression was correlated with histological type, histologic grade, stage, T classification, N classification, and survival status." (PMID 31882722, 2019). "In addition, multivariate analysis indicated MAST2 expression was an independent risk factor for RFS in liver cancer patients (HR = 1.517, 95%CI: 1.059–2.172, p = 0.023)." (PMID 31882722, 2019). "Our study demonstrated that MAST2 could become a novel diagnostic and prognostic biomarker for liver cancer patients." (PMID 31882722, 2019). "Together with T classification (p < 0.001) and residual tumor (p = 0.006), MAST2 expression (HR = 2.110, 95%CI: 1.467–3.035, p = 0.000) was independent risk factor for OS in liver cancer patients after adjusting the other variables correlated with OS (stage, T classification, and residual tumor)." (PMID 31882722, 2019). "Pathogenic conditions associated with aberrant expression of ODF2L, MAST2 and KIF23 include ciliopathy, liver cancer and chronic myeloid leukemia, respectively." (PMID 37026480, 2023). "In conclusion, our study found upregulation of MAST2 in liver cancer, which corresponded with tumor progression and poor prognosis." (PMID 31882722, 2019). "In this study, The Cancer Genome Atlas database was used to study the MAST2 mRNA expression in liver cancer, and Chi-squared tests were performed to test the correlation between clinical features and MAST2 expression." (PMID 31882722, 2019). "The prognostic value of MAST2 in liver cancer was assessed through Kaplan–Meier curves as well as Cox analysis." (PMID 31882722, 2019). "We also found that the upregulation of MAST2 was distinct in different clinical features of liver cancer, such as histologic grade, stage and T classification." (PMID 31882722, 2019). "Kaplan-Meier curves were used to estimate the prognostic role of MAST2 in patients with liver cancer." (PMID 31882722, 2019). "Our studies showed the abnormal expression and prognostic effects of MAST2 in liver cancer, which broadened the field of scientific research on MAST2." (PMID 31882722, 2019). "Our results showed MAST2 was upregulated in liver cancer, and the area under the curve (AUC) was 0.925 and indicated powerful diagnostic capability." (PMID 31882722, 2019). "MAST2 is a microtubule-associated serine/threonine kinase that interacts with the Protocadherin-LKC, a recently proposed tumor suppressor gene for colon and liver cancers, which mediates contact inhibition of cell proliferation." (PMID 33902690, 2021). "Moreover, high MAST2 expression was associated with poor OS and RFS in patients, which suggested the prognostic role of MAST2 in liver cancer." (PMID 31882722, 2019). "Our results showed the overexpression of MAST2 in liver cancer." (PMID 31882722, 2019). "The specific role of MAST2 in liver cancer needs more elucidation." (PMID 31882722, 2019).
liver cancer (continued). "The role of MAST2 in liver cancer has not been well elucidated, which is the aim of our study." (PMID 31882722, 2019).
glioblastoma (3 papers, 2013 to 2019). The most malignant astrocytic tumor (WHO grade IV). "Using a subcutaneous xenograft mouse model, we also demonstrated that glioblastoma tumor growth requires MAST2 expression." (PMID 23717670, 2013). "Both the anti-apoptotic and pro-proliferative molecular functions observed suggest that MAST2 behaves as an oncoprotein in glioblastoma." (PMID 23717670, 2013). "Stable knockdown of MAST2 resulted in significantly enhanced cell death in U87 glioblastoma cells upon co-treatment with TRAIL and the proteasome inhibitors MG132 and epoxomicin." (PMID 23717670, 2013). "Our data demonstrate an increase in apoptosis sensitivity and diminished tumor growth upon MAST2 knockdown in glioblastoma cells, thereby suggesting an oncogenic function for this poorly analyzed kinase." (PMID 23717670, 2013). "The effect of MAST2 in promoting tumor cell proliferation has been reported in glioblastoma." (PMID 31882722, 2019). "Furthermore, MAST2 influences glioblastoma tumor growth, potentially as an apoptosis suppressor." (PMID 30773781, 2019). "The protein is significantly expressed in the glioblastoma cell line U87, whereas MAST2 expression is absent in human cortex tissue, which consists of many astrocytes, probably constituting the cells-of-origin for glioblastoma." (PMID 23717670, 2013).
esophageal cancer (2 papers, 2013 to 2019). A primary or metastatic malignant neoplasm involving the esophagus. "Although MAST2 has not been previously associated with apoptosis regulation and tumorigenesis, according to the Oncomine database, MAST2 mRNA is overexpressed in esophageal cancer, pancreatic cancer and sarcoma samples." (PMID 23717670, 2013). "Several expression studies submitted to Oncomine have demonstrated MAST2 mRNA overexpression in esophageal cancer, pancreatic cancer and sarcomas." (PMID 23717670, 2013).
Azoospermia (1 paper, 2022). Absence of any measurable level of sperm,whereby spermatozoa cannot be observed even after centrifugation of the semen pellet. "Mutations in MAST2 have is associated with non-obstructive azoospermia." (PMID 34190021, 2022).
colon cancer (1 paper, 2017). "The AS of CALD1, COL6A3, FN1, MAST2, LGR5 and ITGB4 were previously validated in colon cancer using RT-PCR24, while CLSTN1, AUP1, CTNND1, CALD1 and COL6A3 were shown to exhibit tumour-specific splice variants in colon, bladder and prostate cancers." (PMID 28592875, 2017).
COVID-19 (1 paper, 2021). A disease caused by infection with severe acute respiratory syndrome coronavirus 2. "MAST2 shows an association with red blood cell distribution width, which was identified recently as a biomarker of COVID-19 mortality." (PMID 34835087, 2021).
Infertility (1 paper, 2023). "Since MAST2 was the first of the MAST kinases to be discovered in the testis in mice, it was not surprising that MAST2 was reported to be associated with infertility in humans." (PMID 37569286, 2023).
thrombophilia (1 paper, 2021). A condition characterized by an abnormally high level of thrombi. "This study identifies a novel thrombophilia-causing Arg89Gln variant in the MAST2 gene that is here proposed as a new molecular player in the etiology of VTE by interfering with hemostatic balance of endothelial cells." (PMID 33465109, 2021). "Using a WES approach, we identified the MAST2 Arg89Gln variant as the disease causing variant responsible for inherited thrombophilia in an extended family of French origin." (PMID 33465109, 2021). "Our results pave the way for adding MAST2 to the list of genes to be sequenced and looked for in thrombophilia families with unprovoked VTE." (PMID 33465109, 2021). "However, our results pave the way for adding MAST2 to the list of genes to be sequenced and looked for in thrombophilia families with unprovoked VTE." (PMID 33465109, 2021).
tumor (11 papers, 2013 to 2025). "Univariate analysis selected that stage (p < 0.001), T classification (p < 0.001), residual tumor (p = 0.042) and expression of MAST2 (p = 0.005) were associated with RFS." (PMID 31882722, 2019). "Importantly, MAST2 was an independent risk factor for patients’ prognosis after adjusting for other risk factors including stage, T classification, and residual tumor." (PMID 31882722, 2019). "Overexpression of these fused gene products lead to enhanced proliferation in a benign breast cell line and RNAi-mediated knockdown of MAST2 in a cancer cell line with MAST2 gene fusions led to reduced growth and reduced tumor formation in mice xenografts." (PMID 37569286, 2023). "Univariate analysis selected several variables correlated with OS, including stage (p = 0.001), T classification (p < 0.001), residual tumor (p = 0.003) and expression of MAST2 (p < 0.001)." (PMID 31882722, 2019). "The xenograft tumor mouse model data supports the notion that MAST2 protein is required for tumor progression, possibly because of its anti-apoptotic potential." (PMID 23717670, 2013). "Our Oncomine database searches revealed an overexpression of PAICS, MALAT1 and MAST2 mRNA in various tumor entities." (PMID 23717670, 2013). "PAICS, an enzyme required for de novo purine biosynthesis, the long non-coding RNA MALAT1 and the MAST2 kinase are overexpressed in certain tumor entities and capable of suppressing apoptosis in human cells." (PMID 23717670, 2013). "Additionally, high mRNA expression levels of genes such as RAD54L (p = 3.3 × 10−6), MAST2 (p = 4.1 × 10−2), and CCHCR1 (p = 1.4 × 10−2) were associated with shorter DFS, further highlighting their role in tumor aggressiveness." (PMID 40227503, 2025). "Further studies showed that MAST2 overexpression promotes cell survival and cell growth, and the knock-down of MAST2 led to reduced tumor growth in a xenograft tumor mouse model, supporting a role of MAST2 in tumor progression that is characteristic of an oncogene." (PMID 37569286, 2023). "The tumor promoting effects of MAST2 may provide a reasonable explanation for the phenomenon in our research that patients with advanced stage and worse status showed high MAST2 expression." (PMID 31882722, 2019). "Boxplots showed the differences in MAST2 expression by tumor vs adjacent normal tissue." (PMID 31882722, 2019). "Stable knockdown of MAST2 in U87 cells strongly diminished tumor growth in immunocompromised mice." (PMID 23717670, 2013). "Moreover, the AUC of MAST2 suggest a potentially important value in tumor diagnosis and prognosis." (PMID 31882722, 2019). "Notable examples, such as FOXQ1, MAST2, and CDH4, were found to play a role in hair follicle development and human cancer, signal transduction, and tumor repression, respectively." (PMID 23349834, 2013). "Collectively, our tumor expression analysis of PAICS, MALAT-1 and MAST2 confirmed the overexpression of all three genes in various tumor entities, thereby supporting the tumor relevance of candidate genes isolated by functional yeast survival screenings of tumor-derived cDNA libraries." (PMID 23717670, 2013). "The overexpression of these MAST2 and MAST1 gene fusions displayed a proliferative effect; however, the function and (tumor) biology of the wildtype MAST proteins were not further investigated." (PMID 23717670, 2013).
cancer (9 papers, 2009 to 2025). A tumor composed of atypical neoplastic, often pleomorphic cells that invade other tissues. "Finally, MAST2 is a kinase associated with microtubules and is involved in intracellular signaling: kinases represent attractive druggable targets for cancer therapy." (PMID 23717670, 2013). "It is worth noting that the first exon of MAST2 is not just occupied by BORIS in K562 cells but is also aberrantly expressed in cancer cells together with BORIS expression." (PMID 27588042, 2016).
infection (2 papers, 2018 to 2025). The state of being infected such as from the introduction of a foreign agent such as serum, vaccine, antigenic substance or organism. "The kinase-substrate phosphomotif pattern analysis revealed several kinases, including EEF2K, HASPIN, MAPK9, MAST2, and Spleen tyrosine kinase (SYK), that can phosphorylate multiple NiV proteins at various sites, suggesting regulatory roles during infection." (PMID 41424949, 2025).
neurodegenerative disease (1 paper, 2025). A disorder of the central nervous system characterized by gradual and progressive loss of neural tissue and neurologic function. "Based on the evidence from the Open Target Platform, GCNT4 and MAST2 are related to neurodegenerative disease and measurements of erythrocyte count, BMI, LDL and TC; whereas CRTAC1 is related to body fat percentage and measurements of HDL and TG." (PMID 40830362, 2025).
MAST2 also shares sentences with these, for which no sentence is quoted: pancreatic cancer (2 papers); chronic myeloid leukemia (1); ciliopathy (1); diabetes (1); fibrosarcoma (1); sarcoma (1); Stroke (1); type 1 diabetes (1); Type 2 diabetes (1); venous thromboembolism (1); Venous thrombosis (1).